SLC11A2 (solute carrier family 11 member 2)
Diseases named in the same sentence as SLC11A2 in open-access papers (continued):
Sharing a sentence is not in itself a finding about the gene and the disease.
amyotrophic lateral sclerosis (1 paper, 2014). Amyotrophic lateral sclerosis (ALS) is a neurodegenerative disease characterized by progressive muscular paralysis reflecting degeneration of motor neurons in the primary motor cortex, corticospinal tracts, brainstem and spinal cord. "Similarly, C allele of SNP rs407135 on the DMT1 encoding gene SLC11A2 is associated with shorter disease duration in cases of spinal onset amyotrophic lateral sclerosis." (PMID 27355037, 2014).
depression (1 paper, 2021). "For the depression PHQ score, two significant gene × blood VD interactions were identified at SLC11A2 and HIGD1C (rs117102029, p = 4.02 × 10−8)." (PMID 34684344, 2021). "In addition, we identified multiple candidate genes which interacted with vitamin D for the depression PHQ score, such as SLC11A2 and HIGD1C." (PMID 34684344, 2021).
Infertility (1 paper, 2023). "In addition to the promise of treating infertility, SLC11A2 could in the future be applied by pathologists to determine the source of ovarian tumors." (PMID 36670142, 2023).
Insulin resistance (1 paper, 2022). Increased resistance towards insulin, that is, diminished effectiveness of insulin in reducing blood glucose levels. "In this sense, we have found an upregulation of different genes related to hypoxia regardless of the degree of insulin resistance, such as ANGPTL4, LPL, S100A8, SLC11A2, HBB, HBA2, and HBD." (PMID 35625760, 2022).
Iron-refractory iron deficiency anaemia (1 paper, 2012). "Iron-refractory iron deficiency anaemia (IRIDA) is a rare disorder which was linked to mutations in two genes (SLC11A2 and TMPRSS6)." (PMID 22509377, 2012).
lung adenocarcinoma (1 paper, 2023). A carcinoma that arises from the lung and is characterized by the presence of malignant glandular epithelial cells. "The gene expression of SLC3A2, SLC16A1, SLC39A14, SLC39A7, SLC1A5, and SLC11A2 in the lung adenocarcinoma cell line A-549 and H1299 is higher than that in the normal lung epithelial cell line Beas-2B." (PMID 37973895, 2023). "The protein expression of SLC3A2, SLC11A2, SLC1A5, SLC16A1, SLC39A7, SLC39A14 in the lung adenocarcinoma cell line A-549 and H1299 is higher than that in the normal lung epithelial cell line Beas-2B." (PMID 37973895, 2023).
mastitis (1 paper, 2022). Inflammation of breast tissue during lactation or postpartum due to an obstructed duct or infection. "Notably, the genes SLC40A1 and SLC11A2 were involved in the ferroptosis signaling pathway, and SLC40A1 was up-regulated in subclinical mastitis cows vs. healthy cows." (PMID 36204322, 2022).
Mediterranean Fever (1 paper, 2017). "Positive controls were noted to have significantly increased expression of genes associated with the inflammatory response, including CCL5 (chemokine ligand 5), MEFV (Mediterranean Fever, codes for pyrin), SLC11A (solute carrier family 11 member 2), and TNF (tumor necrosis factor) (P < .0001)." (PMID 28943993, 2017).
osteosarcoma (1 paper, 2024). A usually aggressive malignant bone-forming mesenchymal neoplasm, predominantly affecting adolescents and young adults. "Similarly, PEITC causes the ferroptosis, autophagy, and apoptosis of murine osteosarcoma cells by downregulating ferroptosis-inhibiting genes (GPX4 and SLC11A2)." (PMID 38892270, 2024). "Moreover, PEITC induces ferroptosis, apoptosis, and autophagy by downregulating ferroptosis-inhibiting genes (SLC11A2, SLC40A1, and FTH1) in osteosarcoma." (PMID 38892270, 2024).
ovarian cystadenocarcinoma (1 paper, 2023). An adenocarcinoma that arises from the ovary and is characterized by the presence of cystic structures. "Heatmaps were drawn using the top 10 genes that were positively correlated with SLC11A2 expression in ovarian cystadenocarcinoma." (PMID 36670142, 2023).
ovarian endometriosis (1 paper, 2024). A non-neoplastic disorder characterized by the growth of endometrial tissue in the ovaries. "Comparable, Slc11a2 expression is elevated in ovarian endometriosis, a disease of the female reproductive tract associated with iron and related ovarian carcinogenesis." (PMID 38464972, 2024).
ovarian serous carcinoma (1 paper, 2023). "The CbioPortal database found that the genomic change rate of the SLC11A2 gene in ovarian serous carcinoma was 1%." (PMID 36670142, 2023). "Immunohistochemical results showed that SLC11A2 protein was strongly positive in ovarian serous carcinoma primary foci, omentum metastases, and normal fallopian tube mucosa." (PMID 36670142, 2023). "The Human Protein Atlas database immunohistochemical staining showed that SLC11A2 protein was highly expressed in ovarian serous carcinoma and not expressed in normal ovarian tissue." (PMID 36670142, 2023).
type 2 diabetes (1 paper, 2025). "In patients with type 2 diabetes, the expression of ferroportin (FPN) and solute carrier family 11 member (SLC11A2) is increased in the intestine, associated with elevated iron stores and serum hepcidin levels." (PMID 40871742, 2025).
infection (11 papers, 2011 to 2025). The state of being infected such as from the introduction of a foreign agent such as serum, vaccine, antigenic substance or organism. "The overwhelming majority of DEGs annotated in the lysosome pathway were downregulated, with the exception of Slc11a2 (formerly known as Nramp 2), one of the minor lysosome membrane proteins overexpressed in both infection libraries." (PMID 22216095, 2011). "A clear difference in expression of iron regulatory genes was observed with a consistent and significant down-regulation of FTH1, SLC11A1, SLC11A2, HMOX1 and TFRC in animals controlling the infection." (PMID 24505407, 2014).
tumor (7 papers, 2013 to 2025). "In this study, the SLC11A2 mRNA was initially poorly expressed in LUAD tumor tissues, while the protein encoded by it was highly expressed, suggesting that the SLC11A2 gene may be regulated epigenetically at the post-transcriptional level." (PMID 36117156, 2022). "Of these eight genes, four (GNAI3, PCDH7, PSEN1, TNFSF9) were highly expressed in tumor tissues and were associated with poor prognosis, while CD69, SLC11A2, and TLR2 were poorly expressed in tumor tissue and were associated with good prognosis." (PMID 36117156, 2022). "Differential analysis showed that GNAI3, PCDH7, PSEN1 and TNFSF9 were highly expressed in tumor tissues, while ADM, CD69, SLC11A2 and TLR2 were opposite." (PMID 36117156, 2022).
cancer (6 papers, 2020 to 2024). A tumor composed of atypical neoplastic, often pleomorphic cells that invade other tissues. "SLC11A2 is upregulated in cancers, thus providing an efficient mechanism for cancer cells to accumulate iron in support of their growth and proliferation." (PMID 38339256, 2024). "Knockdown of SLC11A2 has a significant promoting effect on platinum-induced cancer apoptosis, which makes it possible to reduce the dose of platinum in clinical practice and reduce side effects and drug resistance recurrence." (PMID 36670142, 2023). "The results show that the expression of SLC11A2 is significantly increased in various cancer types compared to normal tissue." (PMID 36670142, 2023). "And we found that MTF1 expression had a positive correlation with the expression levels of SLC31A1 (R = 0.17, p < 0.001), SLC11A2 (R = 0.33, p < 0.001) in pan-cancer." (PMID 37380924, 2023). "We further analyzed SLC11A2 expression between 33 human cancers and their normal tissues using expression data retrieved from the pooled TCGA and GTEx data using the GEPIA2 tool." (PMID 36670142, 2023). "Moreover, the heatmap confirmed the positive relationship between MTF1 and SLC31A1 and SLC11A2 in almost all cancer types." (PMID 37380924, 2023). "The carcinogenesis of iron ions has a broader research basis, but as a key molecule in iron transport, the role of SLC11A2 in malignant tumors remains unclear." (PMID 36670142, 2023).
hematologic tumors (1 paper, 2024). "Interestingly, the expression levels of most FRGs, including SLC38A1, SLC11A2, and HMOX1, were found to be lower in CML samples compared to other types of hematologic tumors." (PMID 39026664, 2024).
psychiatric disorder (1 paper, 2021). A disorder characterized by behavioral and/or psychological abnormalities, often accompanied by physical symptoms. "Nevertheless, no studies have shown a direct link between VD and the effects of SLC11A2 and HIGD1C genes on the nervous system and psychiatric disorders." (PMID 34684344, 2021).
SLC11A2 also shares sentences with these, for which no sentence is quoted: Alzheimer disease (3 papers); Cerebral ischemia (3); glioma (3); aceruloplasminemia (2); cognitive deficits (2); hypochromic anemia (2); Sepsis (2); achondroplasia (1); acute myocardial infarction (1); atransferrinemia (1); atrophic gastritis (1); chronic heart failure (1); chronic obstructive pulmonary disease (1); cognitive decline (1); colorectal tumor (1); congenital sideroblastic anemias (1); Ewing sarcoma (1); experimental autoimmune encephalomyelitis (1); ferroportin disease (1); glioblastoma (1); hematopoietic diseases (1); hemorrhagic stroke (1); hyperferritinemia (1); Hyperglycemia (1); hypertrophic cardiomyopathy (1); hypochromic microcytic anemia (1); iron disorder (1); ischemic stroke (1); kidney cancer (1); leukemia (1).
A further 17 diseases each share a sentence with SLC11A2 in 1 paper.